AKR1C3 (aldo-keto reductase family 1 member C3)
Diseases named in the same sentence as AKR1C3 in open-access papers (continued):
Sharing a sentence is not in itself a finding about the gene and the disease.
cancer (81 papers, 2007 to 2025). A tumor composed of atypical neoplastic, often pleomorphic cells that invade other tissues. "Aldo-keto reductase 1C3 (AKR1C3) is known to be a cancer biomarker correlated to androgen synthesis, and causes drug resistance by direct action on chemotherapeutics and by stabilizing AR splice variant 7 (ARv7)." (PMID 38684887, 2024). "AKR1C3, overexpressed in various cancer tissues, has been associated with disease progression and poor prognosis, playing a pivotal role in resistance to multiple cancer treatment modalities, including radiation, chemotherapy drugs, and steroid drugs." (PMID 38523637, 2024). "Despite this low expression, however, we observed that - also in the stromal compartment - HMGCS2 and AKR1C3 were significantly higher in cancer-associated compared to benign areas." (PMID 31980029, 2020). "As AKR1C3 is implicated in some hormone dependent malignancies and endocrine disorders, drugs selectively inhibiting AKR1C3 are investigated to be used as cancer treatment or drugs treating endocrine disorders for patients where this enzyme is overexpressed." (PMID 33202527, 2020). "The enzyme AKR1C3 has many functions, which include production of prostaglandins, androgens and estrogens, and metabolism of different chemotherapeutics; AKR1C3 is thus implicated in the pathophysiology of different cancers." (PMID 33352741, 2020). "Furthermore, heightened AKR1C3 expression is notably associated with an unfavorable prognosis and resistance to anti-cancer therapies." (PMID 38523637, 2024). "Clinically, this might mean that levels of AKR1C3 in endometrioid endometrial cancer can be determined preoperatively on diagnostic tissue samples to allow prediction of the cancer behavior and stratification of the patients for more personalized treatments." (PMID 33352741, 2020). "Deregulated AKR1C3 expression has been associated with multiple human cancers." (PMID 21134280, 2010). "Human aldo-keto reductase 1C3 (AKR1C3) is a steroid modifying enzyme involved in cancer progression." (PMID 40905588, 2025). "Its second-generation counterpart, KV-49g, stands out as the most effective and selective AKR1C3 inhibitor known, overcoming resistance to anti-cancer agents apalutamide and darolutamide." (PMID 38523637, 2024). "In summary, AKR1C3’s involvement in detoxifying chemotherapeutic agents and regulating ROS levels highlights its significance in chemotherapy resistance across various cancer types." (PMID 38523637, 2024). "AKR1C3 is a multifunctional molecule that is known as a prostaglandin F synthase and hormone activity regulator that regulates the occupancy of hormone receptors and cell proliferation in several cancers." (PMID 38577596, 2024). "These natural products present diverse opportunities for the development of AKR1C3 inhibitors, contributing to the evolving landscape of cancer therapy." (PMID 38523637, 2024). "Contemporary evidence indicates the overexpression of AKR1C3 in tumors, implicating its role as an oncogene in carcinogenesis and cancer progression." (PMID 38523637, 2024). "Over the preceding decade, the pivotal involvement of AKR1C3 in the advancement of hormone-independent cancers has garnered substantial attention within the realm of cancer research." (PMID 38523637, 2024). "The AKR1C3 enzyme has emerged as a key player in carcinoma progression and therapeutic resistance, posing challenges in cancer treatment." (PMID 38523637, 2024). "Overexpression of AKR1C3 is evident at both mRNA and protein levels across diverse carcinoma types, encompassing hormone-dependent and hormone-independent cancers." (PMID 38523637, 2024). "AKR1C3, recognized not only as a biomarker for cancer progression and prognosis but also as a novel target for overcoming therapeutic resistance, presents opportunities for combination therapies with various existing treatments." (PMID 38523637, 2024).
cancer (continued). "Inhibiting AKR1C3 through specific inhibitors has proven effective in halting carcinoma progression, restoring sensitivity to cancer therapies, and enhancing overall prognosis." (PMID 38523637, 2024). "Numerous small molecules have been devised to target the enzymatic activity of AKR1C3, presenting an opportunity to disrupt its involvement in carcinoma progression and resistance to treatment." (PMID 38523637, 2024). "The overexpression of AKR1C3 serves as an oncogenic factor, promoting carcinoma cell proliferation, invasion, and metastasis, and is correlated with unfavorable prognosis and overall survival in carcinoma patients." (PMID 38523637, 2024). "AKR1C3 has recently emerged as a key contributor to the accelerated proliferation and metastasis observed in carcinomas." (PMID 38523637, 2024). "In conclusion, a diverse array of small molecules has been devised to specifically target the enzymatic activity of AKR1C3, offering a promising avenue for impeding its role in carcinoma progression and treatment resistance." (PMID 38523637, 2024). "One gene, AKR1C3, a target of miR-483-5p, was found to be annotated as being involved in the metabolism of two drugs commonly used for the treatment of cancer: doxorubicin and daunorubicin." (PMID 37627212, 2023). "Overexpression of AKR1C3 is detected in many cancer types and it contributes to tumorigenesis and drug resistance via various mechanisms." (PMID 38188684, 2023). "AKR1C3 catalyzes the conversion of aldehydes and ketones to alcohols and plays an important role in multiple cancers." (PMID 37057280, 2023). "Steroid bile acid fused tetrazoles were screened for ability to inhibit aldo–keto reductase 1C3 (AKR1C3), a target for cancer treatment." (PMID 36846371, 2023). "As an NADP(H) oxidoreductase, AKR1C3 is a potential therapeutic target for various malignant tumors and endocrine diseases." (PMID 37166429, 2023). "Several investigations have found that AKR1C3 in cancer cells plays an important role on a more aggressive phenotype." (PMID 35359392, 2022). "In view of cancer treatment, cytotoxicity to target cells in addition to inhibition of AKR1C3 would be a valuable dual activity." (PMID 35208174, 2022). "This further supports the rationale for combining ZAN with ANT therapy in cancers with a high expression of AKR1C3 and/or ABC transporters." (PMID 36297430, 2022). "Although the interaction between AKR1C3 and chemotherapy resistance has already been indicated in many cancers, it is still unclear in EAC." (PMID 34065695, 2021). "AKR1C3 plays crucial roles in multiple cancers, and a low expression level of AKR1D1 predicted poor prognosis and short median survival time." (PMID 34104649, 2021). "AKR1C3, as a key member of the AKR1Cs subfamily, has been identified as a potential novel therapeutic target in multiple types of cancer." (PMID 34065695, 2021). "Over the last few years, aldo-keto reductase family 1 member C3 (AKR1C3) has been associated with the emergence of multidrug resistance (MDR), thereby hindering chemotherapy against cancer." (PMID 33322571, 2020). "In this regard, our results showed that both IBR and ACA selectively inhibited AKR1C3-mediated inactivation of Dau in vitro and in cancer cell lines expressing AKR1C3, thus synergising Dau cytotoxicity to overcome anthracycline resistance." (PMID 33322571, 2020). "In this regard, several AKR1C3 inhibitors have been reported to re-sensitise anthracycline-resistant cancer cells to daunorubicin both in vitro and ex vivo." (PMID 33322571, 2020). "The enzyme aldo-keto reductase 1C3 (AKR1C3) is present in several cancers, in which it is capable of actively metabolising different chemotherapy drugs and decreasing their cytotoxic effects." (PMID 33322571, 2020). "AKR1C3 immunostaining was significantly stronger in cancer epithelia than in benign ones within the same spots (p < 0.0001)." (PMID 31052459, 2019).
cancer (continued). "This study aimed to compare the expression level of AKR1C3 between normal prostatic epithelium and cancer cells in the same patients." (PMID 31052459, 2019). "And the reduction of daunorubicin and idarubicin, which is catalyzed by AKR1C3, also contributes to the resistance of cancer cells to anthracycline treatment." (PMID 28352233, 2017). "There was also a trend for increased expression of AKR1C3 in G2/G3 cancers compared to G1 cancers, but there were also decreased levels of AKR1C3 reported in cancer compared to control endometrium." (PMID 28674494, 2017). "Among these, sulfotransferases (SULT1A1, SULT1A2, SULT1A3) and aldo-keto reductases (AKR1C1, AKR1C2, AKR1C3) were shown to contribute to disease progression and/or represent therapeutic targets in hormone-dependent forms of cancer, including EOC." (PMID 26372729, 2015). "Reduction of PGD2 to 11β-PGF2α correlated linearly with AKR1C3 protein expression in the cancer cell line panel, indicating that PGD2 reduction provides a measurable biomarker of AKR1C3 activity in cells." (PMID 24995161, 2014). "A very recent survey of the expression of AKR1C3 in 2490 surgical samples from 19 types of cancer revealed a strikingly elevated expression of AKR1C3 in a subset of hepatocellular (58%); bladder and gastric (>50%); and non-small cell lung (48%) carcinomas." (PMID 25419901, 2014). "Immunohistochemical staining for AKR1C3 protein expression confirmed the observed expression by western blotting of the controls and the carcinoma." (PMID 23437342, 2013). "Western blot analysis and immunohistochemistry of the protein AKR1C3 showed a marked reduction of its expression in the carcinoma." (PMID 23437342, 2013). "Jaume Farrés (Universitat Autònoma de Barcelona, Spain) continued with his data on AKR1C3 as a highly efficient 9-cis-retinaldehyde reductase which is elevated in different cancer types and is also involved in chemotherapeutic-drug resistance." (PMID 23199258, 2012). "Bioinformatics analysis and biological characterization suggest that elevated AKR1C3 expression in PCa cells not only promotes cancer cell growth but also enhances angiogenesis." (PMID 21134280, 2010). "Forced expression of AKR1C3 was established in human PCa PC-3 and LNCaP cell lines to recapitulate elevated AKR1C3 expression in cancer tissues and to study potential pathological activities of this enzyme in cancerous prostate." (PMID 21134280, 2010). "Bioinformatics data and biological characterization demonstrate that elevated AKR1C3 expression in PCa cells can promote cancer cell growth and cancer cell-mediated angiogenesis." (PMID 21134280, 2010). "AKR1C3 can also be described as a molecule that provides a survival mechanism to promote angiogenesis in cancer progression." (PMID 21134280, 2010). "So far, numerous studies have shown AKR1C3 could serve as a potential biomarker across various cancers." (PMID 40603306, 2025). "AKR1C3 inhibition may overcome chemoresistance across cancers by blocking drug detoxification and ROS modulation." (PMID 41009436, 2025). "Consequently, AKR1C3-driven redox regulation increases therapeutic resistance by protecting cancer cells from ROS-induced cell death." (PMID 40603306, 2025). "The primary mechanism of CRPC progression involves cancer cells utilizing androgenic precursors from the blood or synthesizing de novo testosterone through the upregulation of steroidogenic enzymes, including Cyp17A1, AKR1C3, and 5α-reductase." (PMID 38523637, 2024). "Differential expression of AKR1C3 was common across cancers." (PMID 38577596, 2024). "However, there is relatively limited clinical trials are investigating the efficacy of AKR1C3 inhibitors and prodrugs as anti-cancer treatment strategies." (PMID 38523637, 2024). "Consequently, a burgeoning body of research has been dedicated to the exploration of AKR1C3 inhibitors with the aim of enhancing therapeutic interventions in cancer." (PMID 38523637, 2024).
cancer (continued). "Furthermore, in castration-resistant prostate cancer, androgen biosynthesis from adrenal DHEA is mediated by the action of aldo-keto reductase (AKR)1C3, which promotes cancer growth and invasion by activating androgen receptors." (PMID 39280099, 2024). "Therefore, the inhibition of reducing enzymes such as AKR1C3 represents an engaging pharmacological strategy to overcome cancer drug resistance and restore the antineoplastic activity of the drugs." (PMID 35208174, 2022). "In addition, more studies in AKR1C3 targeted therapy will help improve cancer care in patients with T-ALL." (PMID 35388063, 2022). "AKR1C3 represents a therapeutic target to combat the resistance in many cancers." (PMID 34065695, 2021). "In this regard, we demonstrated that Bruton’s tyrosine kinase (BTK) inhibitors ibrutinib and acalabrutinib efficiently prevented daunorubicin (Dau) inactivation mediated by AKR1C3 in both its recombinant form as well as during its overexpression in cancer cells." (PMID 33322571, 2020). "AKR1C3 has an important role in sex hormone metabolism, which potentially influences cancer cells." (PMID 33352741, 2020). "AKR1C3 also has roles in the metabolism of steroid hormones, as it catalyzes the reduction of androstenedione to testosterone, and estrone to estradiol, which can stimulate cancer cell proliferation." (PMID 33352741, 2020). "Interestingly, AKR1C3 is over-expressed in a variety of cancers and its inhibition leads to the conversion of the PGD2 prostaglandin to PGJ2 prostanoids that presents anti-neoplastic properties." (PMID 30190791, 2018). "Thus, AKR1C3 constitutes a promising anti-cancer target and its inhibitors, among which sulindac, represent potential new leads for anti-cancer drug development." (PMID 30190791, 2018). "Participation of AKR1C3 in cancer development is also well proven." (PMID 28352233, 2017). "Consistently with this, overexpression of AKR1C3 enhances resistance of cancer cells to radiation." (PMID 28352233, 2017). "As AKR1C3 is highly expressed in some human cancers, including HCC, the transcriptional regulation of certain isoforms of the AKR family may be mediated by similar mechanisms." (PMID 26516929, 2015). "Therefore, AKR1C3 has recently been regarded as a potential anti-cancer drug target in both CRPC and ER-positive breast cancer." (PMID 25003082, 2014). "Moreover, three members of aldo-keto reductases (AKRs), AKR1C1, AKR1C2, and AKR1C3, are overexpressed in cancer." (PMID 25243088, 2014). "Because we found a deletion of the 10p14-p15.2 region by aCGH, it is tempting to speculate that one copy of the AKR1C3 gene is truncated by the virus and the other copy is lost during transition to carcinoma." (PMID 23437342, 2013). "AKR1C3-dependent hormone and prostaglandin metabolism is therefore an attractive target for drug development with application to both hormone-dependent and independent cancers." (PMID 22937138, 2012). "AKR1C3 has been shown to be up-regulated in some human cancers." (PMID 21982454, 2011). "Based on the observations that expression of AKR1C3 is elevated in both localized and metastatic PCa, the enzyme might modulate significant pathological activities in cancer development or progression." (PMID 21134280, 2010). "AKR1C1/AKR1C3 was known to inactivate progesterone, which could alter the progesterone/estrogen ratio in certain cancers." (PMID 18034892, 2007). "In addition, AKR1C3 has been shown to be up-regulated in several types of human cancer." (PMID 21982454, 2011). "AKR1C3, a well-known member of the aldo-keto reductase (AKR) superfamily, has been studied extensively in cancer-related biological processes, including cell proliferation and chemosensitivity." (PMID 40055914, 2025).
cancer (continued). "In chemoresistant cancers, their co-overexpression creates a robust antioxidant defense—AKR1C2 clears toxic aldehydes, while AKR1C3 sustains redox balance through GSH and survival pathways." (PMID 41009436, 2025). "Topological analysis of the PPI network, using the STRING database and Cytoscape 3.10.2, identified seven core targets crucial in cancer pathways: CYP3A4, PIK3R1, PIK3CD, ESR1, AKR1C3, EGFR, and CYP19A1." (PMID 39204124, 2024). "The differential expression of PIK3R1, AKR1C3, EGFR, ESR1, PIK3CD, CYP3A4, and CYP19A1 across various cancer types and stages illuminates their potential as biomarkers for cancer progression and prognosis." (PMID 39204124, 2024). "In our previous experiments, IBR and ACA inhibited the AKR1C3-mediated inactivation of DAUN, leading to an increase in its effectiveness against cancer cells." (PMID 36297430, 2022). "AKR1C3 is a NADP(H) oxidoreductase that belongs to the aldo-keto reductase superfamily and has been proposed as a therapeutic target for a variety of cancers and endocrine illnesses." (PMID 35741758, 2022). "The present study confirms the expression of AKR1C3 in HGSC, with immunoreactivity seen in cancer cells, ovarian stroma, and endothelium." (PMID 33352741, 2020). "For this reason, as a future scope of research, we aim to study the mechanisms by which BTK inhibitors target AKR1C3 and AKR1B10 and modulate cell proliferation for potential applications in cancer treatment." (PMID 33322571, 2020). "This study aims to compare the expression level of AKR1C3 between benign prostatic epithelium and cancer cells, and among hormone-naïve prostate cancer (HNPC) and CRPC from the same patients, to understand the role of AKR1C3 in PCa progression." (PMID 31052459, 2019). "This profile revealed the coincidence of elevated expression of AKR1C3 and radioresistance in esophageal KY170R and TE13R cancer cells." (PMID 25419901, 2014). "Aldo-keto reductases overexpressed in our cancer dataset (AKR1C1, AKR1B10, and AKR1C3) are involved in the reduction of retinal to retinol." (PMID 25243088, 2014). "Then, he reported on the identification of cytosolic AKR1C3 and AKR1B10 with retinaldehyde reductase activity, the latter having a possible relevance in cancer." (PMID 23199258, 2012). "Furthermore, AKR1C2, AKR1C3, and AKR1B1 knockdown attenuated the proliferation and invasive ability of cancer cells." (PMID 40361399, 2025). "AKR1C3 catalyses the transformation of ANTs to less potent hydroxy-metabolites, whereas transporters decrease the ANT-effective concentrations by pumping them out of the cancer cells." (PMID 36297430, 2022). "Anti-proliferative IC50 assays were also conducted using a panel of cancer cell lines with varying levels of endogenous AKR1C3 expression in the presence or absence of the AKR1C3 selective inhibitor SN34037." (PMID 34959631, 2021). "In conclusion, the enhanced response of PR-104A after preconditioning with SF was apparent only in cancer cells provided that AKR1C3 is expressed, while its expression in non-cancerous cells did not elicit such a response." (PMID 26950072, 2016). "SULT2B1b depletion was reported to promote AKR1C3 expression, which activates extracellular-signal-regulated kinase 1/2 (ERK1/2) tumor cell survival signal, activates androgen receptors, and induces epithelial-to-mesenchymal (EMT)-like changes that promote cancer progression and invasiveness." (PMID 39280099, 2024). "As NRF2 upregulate a series of detoxification genes and protect cancer cells against insults, our results demonstrated that the sensitivity of nedaplatin may be influenced by other NRF2 downstream genes, including but not limited to AKR1C3, GST, and PSAT1." (PMID 27601007, 2016). "This may be explained by that there is AKR1C3-independent steroid hormone production in most cells, and the data suggest that AKR1C3 is not an effective drug target in most CRPC cancer patients." (PMID 25003082, 2014).